RNU4-85P (RNA, U4 small nuclear 85, pseudogene)
Gene: Small nuclear RNA gene on chromosome 3 (19,996,803 to 19,996,925, forward strand). Ensembl gene ENSG00000201545.
Homologues: Orthologues: chimpanzee U4 (100% identical), macaque U4 (88% identical), guinea pig U4 (63% identical), dog U4 (62% identical), pig U4 (58% identical), rat LOC120102557 (53% identical). Paralogues in human: RNU4-84P (79% identical), RNU4-75P (76% identical), RNU4-17P (72% identical), RNU4-21P (72% identical), RNU4-12P (71% identical), RNU4-13P (71% identical), RNU4-16P (71% identical), RNU4-42P (71% identical), RNU4-44P (71% identical), RNU4-68P (71% identical), RNU4-70P (71% identical), RNU4-76P (71% identical), and 81 more.